ITGB1 (integrin subunit beta 1)
Diseases named in the same sentence as ITGB1 in open-access papers (continued):
Sharing a sentence is not in itself a finding about the gene and the disease.
infection (continued). "Molecular docking, which can well simulate the binding and force between proteins and peptides, was used to simulate the binding of the viral F protein to ITGB1, indicating that the aMPV/C F can tightly bind to ITGB1 via hydrogen bonds and hydrophobic forces, thereby promoting aMPV/C infection." (PMID 38255903, 2024). "In the HUVEC, the blockage of ITGB1 with antibody and inhibition of CAV-1 with filipin or depletion of ITGB1 and CAV-1 encoding genes with siRNA interference caused the noticeable decrease of intracellular leptospires during infection." (PMID 36137081, 2022). "In particular, only the inhibition of ITGB1 in the THP-1 or blockage of both the ITGB1 and CAV-1 in HUVEC could cause the significant decrease of intracellular leptospires during infection." (PMID 36137081, 2022). "To understand what may drive this change in ITGB1 Tm during infection, we monitored the Tm values of functionally related complexes and proteins from CORUM." (PMID 32041945, 2020). "Furthermore, outside the context of infection, tetraspanins were observed to colocalize with ITGB1, suggesting involvement in ITGB1 internalization." (PMID 32041945, 2020). "Additionally, we uncovered another putative component of the ITGB1 internalization mechanism during infection." (PMID 32041945, 2020). "ITGB1 mRNA expression in human immortalised oviductal epithelial OE-E6/E7 cells was significantly increased following 24 h of exposure to 1.0 multiplicity of infection (MOI) C. trachomatis compared to control (P < 0.05)." (PMID 29500127, 2018). "Moreover, to determine whether ITGB1 served as a receptor for aMPV/C infection in A549 cells, we transfected human and avian ITGB1 plasmids into A549 cells." (PMID 38255903, 2024). "The data suggest that powerful invasive L. interrogans transmigrate through vessel wall maintained high viability and the ITGB1 and CAV-1 mediate the transcytosis of the spirochete during infection." (PMID 36137081, 2022). "The data suggest that the ITGB1 in THP-1 and both the ITGB1 and CAV-1 in HUVEC mediate the internalization of the spirochete during infection." (PMID 36137081, 2022). "After infection of leptospires, the relative gene expression of ITGB1 in THP-1, ITGB1 and CAV-1 in HUVEC were up-regulated." (PMID 36137081, 2022). "Relative gene expression of ITGB1, ITGB2 ITGB3 and CAV-1 in THP-1 or HUVEC were analysed by comparing treatment of 4h leptospires infection and non-infection." (PMID 36137081, 2022). "The Euclidean distances between protein aggregation profiles indicated that, while ITGB1 and collagen (COL1A1) or fibronectin (FN1) became gradually distant during infection, ITGB1 and CD63 became closer." (PMID 32041945, 2020). "To determine the role of CD63 in ITGB1 internalization and virus production, we performed siRNA-mediated CD63 knockdowns and confirmed knockdown throughout infection and cell viability." (PMID 32041945, 2020). "Genes involved in the control of cell migration were also represented in the HP1 list (e.g. Ccr2, Ccr5, Itga1, Itgb1, Gpr183, Rgs16), with some having an essential role in the recruitment of CD8 T cells in the lung following infection by a pathogen." (PMID 27883012, 2016). "The transient expression of avian ITGB1-rendered porcine and feline non-permissive cells (DQ cells and CRFK cells, respectively) is susceptible to aMPV/C infection." (PMID 38255903, 2024). "Interestingly, the relative expression of ITGB1 in THP-1 and ITGB1/CAV-1 in HUVEC was significantly up-regulated after infection of L. interrogans." (PMID 36137081, 2022). "Together, these results indicate that expression of MUC1 on the cell surface does not form a physical barrier against infection but instead slightly enhances ITGB1-mediated uptake of E. coli inv." (PMID 33824202, 2021). "By contrast, eHEV infection appeared to be unaffected by the absence of ITGB1." (PMID 40571699, 2025).
infection (continued). "Infection of the DOX+ MUC1-YF cells with E. coli inv showed a 30% reduction in the number of infected cells for the subset of MUC1-YF expressing cells compared to DOX− MUC1-YF cells, suggesting that tyrosine residues in the MUC1 CT play a role in ITGB1-mediated bacterial uptake." (PMID 33824202, 2021). "Our results suggest that CD63 may similarly promote ITGB1 internalization during infection, but this was not previously demonstrated." (PMID 32041945, 2020). "We acknowledge that our results demonstrate that Fallopian tube ITGB1 increases in response to C. trachomatis infection but do not explain how, the effect endures following elimination of the infection in the face of oviductal epithelial cell turnover and regeneration." (PMID 29500127, 2018).
adenocarcinoma (5 papers, 2015 to 2024). A common cancer characterized by the presence of malignant glandular cells. "Three proteins, namely, ITGB1, FBN1, and THBS1, were identified as common across the examined adenocarcinomas, DCIS and BC of all grades." (PMID 36010848, 2022). "Finally, could serological detection of proteins such as ITGB1, FBN1, and THBS1 be employed as a general screening tool for adenocarcinomas ?" (PMID 36010848, 2022).
bacterial infection (3 papers, 2022 to 2023). "The expression of invasin protein in E. coli can promote bacterial invasion of host cells, and ITGB1 functions as a receptor for invasin in the bacterial infection pathway, which confirming our viewpoint." (PMID 37085748, 2023). "It implies that ITGB1 plays a vital role in Rap1 signaling pathways in human defense systems against bacterial infection." (PMID 35216171, 2022).
cardiovascular disease (2 papers, 2024 to 2025). "Besides, volociximab, a monoclonal antibody targeting ITGB1, has demonstrated potential in anti-cardiovascular disease." (PMID 39062199, 2024). "Developing ITGB1-based drugs may provide more precise and effective therapeutic interventions, improving the prognosis of patients with MI and other cardiovascular diseases." (PMID 39062199, 2024).
kidney disease (2 papers, 2020 to 2022). "Supporting the key role of ITGB1 in the kidneys, the β1-integrin-knockout mice develop severe proteinuric kidney disease from birth, and patients with Abatacept-stabilized β1-integrin activation are protected from B7-1-positive proteinuric kidney disease." (PMID 35628588, 2022). "It has been documented that ITGB1 inhibition can attenuate the development of kidney diseases." (PMID 33299380, 2020).
digestive system cancer (1 paper, 2025). A primary or metastatic malignant neoplasm involving any part of the digestive system. "After comparing the co-expressed genes in these five digestive system cancers, five genes, PKD2, CDH11, OSMR, ITGB1, and BNC2, were further identified as being associated and interacting with ITGAV through the Venn diagram." (PMID 40018050, 2025).
infectious disease (1 paper, 2025). A disorder directly resulting from the presence and activity of a microbial, viral, or parasitic agent in humans. "This study not only establishes physiologically relevant immuno‐lung organoid models for modeling macrophage‐mediated tissue damage, but also identifies a previous unrecognized role of the THBS1‐(ITGA3+ITGB1) pathway in driving lung cell senescence during infectious disease." (PMID 40712141, 2025).
ITGB1 also shares sentences with these, for which no sentence is quoted: Breast Invasive Carcinoma (4 papers); heart failure (4); co-infection (3); depression (3); diabetes (3); gallbladder cancer (3); keloid (3); systemic lupus erythematosus (3); acute coronary syndrome (2); AIDS (2); breast adenocarcinoma (2); cardiomyopathy (2); chronic lymphocytic leukemia (2); colorectal tumor (2); intracranial hemorrhage (2); Lipedema (2); metabolic disease (2); multiple myeloma (2); multiple sclerosis (2); acute myocardial infarction (1); anaplastic astrocytoma (1); anemia (1); anencephaly (1); ankylosing spondylitis (1); Anxiety (1); aplastic anemia (1); Arthritis (1); basal cell carcinoma (1); bladder urothelial carcinoma (1); bone tumor (1).
A further 74 diseases each share a sentence with ITGB1 in 1 paper.